REPIN1 (replication initiator 1)
Description:
Sequence-specific double-stranded DNA-binding protein. Binds ATT-rich and T-rich DNA sequences and facilitates DNA bending. May regulate the expression of genes involved in cellular fatty acid import, including SCARB1/CD36, and genes involved in lipid droplet formation (By similarity). May regulate the expression of LCN2, and thereby influence iron metabolism and apoptosis-related pathways (By similarity). May regulate the expression of genes involved in glucose transport (By similarity).
Synonyms: RIP60; ZNF464; AP4; H_DJ0584D14.12; Zfp464
Tractability: PROTAC: ubiquitination databases record sites on it; its protein half-life has been measured.
Gene: Protein-coding gene on chromosome 7 (150,368,071 to 150,374,045, forward strand). Ensembl gene ENSG00000214022.
Subcellular location: Nucleus; Cytoplasm, cytosol
Subcellular location (Human Protein Atlas): Nucleoplasm
Gene Ontology:
Molecular function: RNA binding; sequence-specific DNA binding; DNA-binding transcription activator activity, RNA polymerase II-specific; RNA polymerase II cis-regulatory region sequence-specific DNA binding
Biological process: regulation of fatty acid transport; regulation of transcription by RNA polymerase II; positive regulation of transcription by RNA polymerase II
Cellular component: nucleoplasm; cytosol; nuclear membrane; nucleus
Genetic constraint (gnomAD): Loss-of-function variants: 5 observed, 7.65 expected, observed/expected ratio (o/e) 0.65, 90% interval 0.34 to 1.37. That is too few expected variants to judge how well the gene tolerates losing a copy. Missense variants: 854 observed, 803.25 expected, observed/expected ratio (o/e) 1.06, 90% interval 1 to 1.12. Synonymous variants: 410 observed, 348.44 expected, observed/expected ratio (o/e) 1.18, 90% interval 1.08 to 1.28.
Homologues: Orthologues: chimpanzee REPIN1 (99% identical), macaque REPIN1 (97% identical), rabbit REPIN1 (90% identical), dog REPIN1 (90% identical), pig REPIN1 (89% identical), guinea pig REPIN1 (86% identical), rat Repin1 (85% identical), mouse Repin1 (83% identical), Drosophila melanogaster CG14667 (13% identical), Caenorhabditis elegans C46E10.8 (8% identical).
Diseases named in the same sentence as REPIN1 in open-access papers:
REPIN1 is named in the same sentence as 19 diseases in open-access papers, as found by Europe PMC text mining. Sharing a sentence is not in itself a finding about the gene and the disease. The quoted sentences say what the papers report.
glioma (4 papers, 2020 to 2021). A benign or malignant brain and spinal cord tumor that arises from glial cells (astrocytes, oligodendrocytes, ependymal cells). "For example, miR-127 affected cell proliferation, migration, invasion, and survival of patients in glioma by targeting REPIN1." (PMID 32051829, 2020). "As for miR-127, it has been reported to regulate cell proliferation, migration, invasion, and prognosis of patients by mediating replication initiator 1 (REPIN1) in glioma." (PMID 32051829, 2020). "However, high REPIN1 expression was found to inhibit cell proliferation, migration and invasion in glioma cells." (PMID 33344452, 2020).
breast carcinoma (3 papers, 2020 to 2021). "It was believed that REPIN1 could contribute to breast cancer tumorigenesis." (PMID 33344452, 2020).
Obesity (3 papers, 2018 to 2023). Accumulation of substantial excess body fat. "Repin1 has been suggested as candidate gene for obesity and dyslipidemia by regulating key genes of lipid metabolism and lipid storage." (PMID 30442920, 2018). "Whereas therapeutic strategies to reduce Repin1 expression are of interest in human obesity, the availability of lipids during regeneration after liver surgery is of high importance." (PMID 30442920, 2018).
metabolic syndrome (2 papers, 2013 to 2018). A cluster of metabolic risk factors for CARDIOVASCULAR DISEASES and TYPE 2 DIABETES MELLITUS. "Hepatic Repin1 deficiency caused dyslipidemia in plasma at baseline and altered hepatic lipid content after PH." (PMID 30442920, 2018). "The identification of genes through the use of congenic sub-lines has been successfully reported, including genes such as Mpdz (influencing the predisposition to alcohol physiological dependence), and Repin1 (associated to metabolic syndromes)." (PMID 24386249, 2013).
steatosis (2 papers, 2018 to 2023). Increased lipid within the cytoplasm of cells. "Generally, in vitro steatosis was accompanied by a slightly increased Repin1 expression in wildtype hepatocytes." (PMID 30442920, 2018). "In vitro steatosis experiments with primary hepatocytes also revealed attenuated lipid accumulation and occurrence of smaller lipid droplets in Repin1-deficient cells, while no direct effect on proliferation in HepG2 cells was observed." (PMID 30442920, 2018).
cervical cancer (1 paper, 2022). A primary or metastatic malignant neoplasm involving the cervix. "Of these, AC099343.2 was identified as an autophagy-related lncRNA signature for potential prognostic biomarkers of patients with cervical cancer; REPIN1." (PMID 36226190, 2022).
diabetes (1 paper, 2025). "Repin1 has previously been identified as a genetic factor contributing to high-fat diet protection against diabetes in the OK/BB rats, while the present genetic analysis did not reveal a difference between DP and DR Repin1." (PMID 41042382, 2025).
Insulin resistance (1 paper, 2023). Increased resistance towards insulin, that is, diminished effectiveness of insulin in reducing blood glucose levels. "Previous studies have suggested that REPIN1 may be involved in fat metabolism and insulin resistance." (PMID 37749079, 2023).
iron overload (1 paper, 2023). "We revealed that sh-Repin1 therapy can rescue bone loss in an iron-overload-induced osteoporosis mouse model." (PMID 37749079, 2023). "In our research, we found that replication initiator 1 (REPIN1) was highly expressed in bone tissue from elderly osteoporosis patients with iron overload." (PMID 37749079, 2023). "We used siRNA and plasmid to knockdown or overexpress Lcn2, respectively, which partially offset or replicated the therapeutic effect of sh-Repin1 in iron-overload-induced osteogenesis dysfunction." (PMID 37749079, 2023). "The results in animal models preliminarily confirmed the conclusion that REPIN1 plays a key regulatory role in iron-overload-induced osteoporosis." (PMID 37749079, 2023). "In brief, combined with the findings of the GEO database, we repeatedly verified the key role of Repin1 in iron-overload-induced osteoporosis from multiple aspects through clinical specimens, in vitro and in vivo experiments, and bioinformatics analysis after RNA-seq." (PMID 37749079, 2023).
osteoporosis (1 paper, 2023). A condition of reduced bone mass, with decreased cortical thickness and a decrease in the number and size of the trabeculae of cancellous bone (but normal chemical composition), resulting in increased fracture incidence. "REPIN1 and iron were found to be elevated in osteoporosis, and combined with the current role of iron overload in osteoporosis, our research successfully linked REPIN1 and osteoporosis through iron metabolism-related pathways." (PMID 37749079, 2023). "To verify the results of GEO data analysis, we collected bone tissue samples from clinical osteoporosis patients to detect the expression level of REPIN1." (PMID 37749079, 2023). "It is worth noting that we combined bioinformatics analysis through in vivo and in vitro experimental verification for the first time and found the key role of REPIN1 in iron metabolism-related osteoporosis." (PMID 37749079, 2023). "We found that the expression of REPIN1 was increased and that there was also accumulation of iron in bone tissue from osteoporosis patients." (PMID 37749079, 2023). "In summary, based on the results of clinical specimens, animal models and in vitro experiments, for the first time, we proved the key role of REPIN1 in iron metabolism-related osteoporosis." (PMID 37749079, 2023). "We observed similar therapeutic effects in the FAC and OVX models, further confirming the key regulatory role of REPIN1, which will be important for the subsequent search for common therapeutic targets for multiple types of osteoporosis." (PMID 37749079, 2023). "This phenomenon has also been verified in the OVX model, indicating that Repin1’s regulation of osteoporosis is universal." (PMID 37749079, 2023). "Based on the raw data from the GEO database, we first found a trend of high expression of Repin1 in osteoporosis patients and then verified this finding in clinical specimens." (PMID 37749079, 2023). "We compared the gene expression of normal elderly with elderly osteoporosis patients and found that the expression of REPIN1 increased in the osteoporosis group (log FC = 6.33)." (PMID 37749079, 2023). "We found that the expression level of REPIN1 was indeed increased in osteoporosis patients." (PMID 37749079, 2023). "In this research, we found that there is indeed evidence of iron accumulation in the bone tissue of patients with osteoporosis and REPIN1, as an origin specific DNA binding protein, may play a key role in this process." (PMID 37749079, 2023). "In summary, we found the therapeutic effect of sh-Repin1 in saving bone mass in osteoporosis models induced by iron overload and OVX, which fully proved that Repin1 plays a universal role in various types of osteoporosis." (PMID 37749079, 2023).
cancer (1 paper, 2021). A tumor composed of atypical neoplastic, often pleomorphic cells that invade other tissues. "REPIN1 activity has been reported in transcriptional repression of cell cycle inhibitor p21, regulating cell cycle progression or inducing the epithelial–mesenchymal transition (EMT) and migration in cancer cells." (PMID 34360960, 2021).
REPIN1 also shares sentences with these, for which no sentence is quoted: esophageal cancer (1 paper); giant cell tumor of bone (1); Hepatic steatosis (1); hepatocellular carcinoma (1); infertile (1); melanoma (1); thyroid cancer (1); trisomy 21 (1).